FANCC (FA complementation group C)
Diseases named in the same sentence as FANCC in open-access papers (continued):
Sharing a sentence is not in itself a finding about the gene and the disease.
diabetes (1 paper, 2018). "We found metabolites driven by FANCC are associated not only with cancer or aging but also clearly with inflammation and diabetes, which are certainly part of mechanisms for reduced tumorigenicity initiated by FANCC." (PMID 29930218, 2018). "In this study, we showed how FANCC affected cellular biological functions through systematically studying FANCC-driven metabolic features and reveled the metabolomics aspects of inflammation, aging, or/and diabetes are associated with cancer at the metabolic level." (PMID 29930218, 2018). "To investigate the roles of metabolite alterations triggered by FANCC in the diseases with metabolite dysfunction such as diabetes, inflammation and cancer, we performed molecular pathway and network analyses using Ingenuity Pathway Analysis (IPA)." (PMID 29930218, 2018). "This is because when FANCC is elevated, the tumorigenecity is mitigated in coordinated with the changed signature metabolites for aging, inflammation or diabetes." (PMID 29930218, 2018). "Detailed analyses of these specific differences were clearly indicated that FANCC may play roles in inflammation, diabetes, aging as well as cancer." (PMID 29930218, 2018). "Furthermore, we found the metabolites leading to another metabolite-disorder diabetes-mellitus (DM) (fumaric acid, fatty acid, D-glucose, carbon monoxide, collagens, 2-oxoglutaric acid) were altered in FANCC-high cells." (PMID 29930218, 2018). "This was incited by the unique diabetes-prone phenotype displayed by FANCC-knockout mice, which is not a typical phenotype associated with FA." (PMID 29930218, 2018). "In the recognition of the diabetes-prone phenotype in FANCC knockout mice, that is not a typical clinical complication shown in FA, we decided to metabolically probe the function of FANCC to broaden the knowledge learned from FA." (PMID 29930218, 2018).
Gorlin syndrome (1 paper, 2018). "FANCC is implicated in Gorlin syndrome that has a phenotype including broad nasal root, cleft lip, and cleft palate." (PMID 30631343, 2018).
head and neck squamous cell carcinoma (1 paper, 2008). A squamous cell carcinoma that arises from any of the following anatomic sites: lip and oral cavity, nasal cavity, paranasal sinuses, pharynx, larynx, and salivary glands. "Deletion of FANCC in bladder carcinoma, mutations in young-onset pancreatic cancer and Fanconi Anaemia-C patients, and down-regulation in head and neck squamous cell carcinoma (HNSCC) are reported." (PMID 18990233, 2008).
hepatocellular carcinoma (1 paper, 2010). A malignant tumor that arises from hepatocytes. "We newly identified a single cell line, HuH-7, derived from a hepatocellular carcinoma (HCC), which exhibited a proximal FA pathway defect, ascribable to genetic FANCC inactivation." (PMID 20509860, 2010).
Insulin resistance (1 paper, 2017). Increased resistance towards insulin, that is, diminished effectiveness of insulin in reducing blood glucose levels. "Patients with mutations in FANCA show a mild endocrine phenotype in which height is not severely affected and insulin resistance is mild, whereas mutations in FANCC, which are related to shorter stature, have the least insulin resistance." (PMID 29238724, 2017).
lung adenocarcinoma (1 paper, 2016). A carcinoma that arises from the lung and is characterized by the presence of malignant glandular epithelial cells. "One possibility is that FANCC has multiple functional domains, and that, in males, only the domain encoded by the 3′-end sequence is important, while all domains are associated with susceptibility in female lung adenocarcinoma patients." (PMID 26842001, 2016). "Consistent with the findings of the single SNP/gene analysis, the high-risk FANCC and FANCD1 genotypes were strongly associated with lung adenocarcinoma risk in both males and females." (PMID 26842001, 2016). "Interestingly, one SNP, rs356665, located at the 3′-end of FANCC, was found to be significant in both male and female lung adenocarcinoma patients." (PMID 26842001, 2016).
myelogenous leukemia (1 paper, 2011). "Consistent with this, in FANCC-deficient murine hematopoietic stem cells, TNF-αoverproduction results in bone marrow hypoplasia, and long-term exposure of these cells to TNF-α induces clonal evolution that leads to myelogenous leukemia." (PMID 21912593, 2011). "Moreover, in FANCC-deficient murine hematopoietic stem cells, overproduction of and hypersensitivity to TNF-α results in bone marrow hypoplasia and long-term exposure of these cells to TNF-α induced clonal evolution that led to myelogenous leukemia." (PMID 21912593, 2011).
osteosarcoma (1 paper, 2024). A usually aggressive malignant bone-forming mesenchymal neoplasm, predominantly affecting adolescents and young adults.
polycystic ovary syndrome (1 paper, 2019). A disorder that manifests as multiple cysts on the ovaries. "Moreover, the genome-wide association studies (GWAS) in European ancestry populations suggest that FANCC is a high risk locus of polycystic ovary syndrome, and FANCI is implicated in age at menopause." (PMID 31535215, 2019).
testis cancer (1 paper, 2024). "Almost all of the top-performing genes were that of over-expression, with PMS2 in THYM; CARD11, LASP1, STIL, POLE, KMT2C, and CLIP1 in testis cancer; ERC1, WRN, OLIG2, FANCC, and ACSL6 in ACC; and SOX2 and NDRG1 in ESCA leading in performance with AUCs ranging 0.832-0.911." (PMID 38491101, 2024).
virus infection (1 paper, 2007). "Twenty-four hours after the virus infection, the FANCC mRNA level was found to be upregulated, while the GAPDH mRNA level remained unchanged." (PMID 19936073, 2007).
cancer (34 papers, 2015 to 2026). A tumor composed of atypical neoplastic, often pleomorphic cells that invade other tissues. "Genomic and pathologic analyses of HCC tissue revealed a TMB-high, TPS, and CPS-high cancer, with mutated DNA damage repair gene FANCC." (PMID 37928536, 2023). "The same authors found that, in cells expressing FANCC at different levels, there are alterations in metabolites associated with aging, inflammation, and cancers." (PMID 32962238, 2020). "Collectively, featured-metabolic alterations are readouts of functional mechanisms underlying reduced tumorigenicity driven by FANCC, demonstrating close links among cancer, aging, inflammation and DM." (PMID 29930218, 2018). "Together, these findings suggest that FANCC is involved in the regulation of various disorders from cancer, aging, to inflammation as well as to DM, consistent with DM-prone mice deficient in FANCC expression." (PMID 29930218, 2018). "The FANCC gene is also well known to predispose to cancer and was recently also suggested in CRC." (PMID 29541405, 2018). "PV were detected in 13 cancer predisposition genes including ATM (n=4), BLM (n=1), BRCA1 (n=1), BRCA2 (n=7), BRIP1 (n=1), CDKN2A (n=1), CHEK2 (n=9), FANCC (n=1), MUTYH (n=10), NBN (n=1), PALB2 (n=1), RAD51D (n=1) and STK11 (n=1)." (PMID 36091166, 2022). "Six pathogenic variants (in BRCA1,BMPR1A,FANCA,FANCC,NBN genes) with cancer related phenotype and three unsolicited variants (in BRCA2,PALB2,RAD50 genes) were reported to patients." (PMID 31937788, 2020). "In our experiments, we found that FANCC proteins regulates the various metabolic signaling pathways that regulate cancer." (PMID 29930218, 2018). "Our study provides the first snapshot of all cellular processes initiated from FANCC, suggesting distinct connections among inflammation, DM, aging and cancer." (PMID 29930218, 2018). "By contrast, the FANCC and EXO1 knockouts are more similar to HR-deficient cancers; defined by general genomic instability and an excess of deletions with microhomology at the breakpoint junction." (PMID 29717121, 2018). "The rearrangement signatures of EXO1 and FANCC knockouts were compared with cancer-derived rearrangement signatures (RS1-RS6)." (PMID 29717121, 2018). "Overall, the cancer promotion signaling was prohibited as shown in red color in FANCC-high cells compared with FANCC-low cells." (PMID 29930218, 2018). "Among these metabolites, docosahexaenoic acid and sphingomyelin were shown at a reduced level in FANCC-high cells, which are indicative of the cellular processes that promote cancer development." (PMID 29930218, 2018). "Identified monoallelic variants in genes linked to autosomal recessive predisposition to cancer such as the ones in RAD50, FANCC, and FANCM might also be relevant for cancer risk." (PMID 35250968, 2022). "FANCC is a member of the FA gene family, which has been mainly studied in FA and cancers." (PMID 35659106, 2022). "Therefore, FANCC, besides joining the FA pathway, can also play important pathway-independent roles in the suppression of cancer formation." (PMID 29930218, 2018). "From these FANCC-induced metabolic changes, we believe there is a principal link among cancer, aging, inflammation, and DM, that mediates many metabolic disorders that can serve as “a low-grade status” of a specific disease, e.g., cancer." (PMID 29930218, 2018).
cancer (continued). "Interestingly, preliminary data on isogenic RKO cancer cells harbouring defects in the proximal FA pathway revealed increased TRAIL-sensitivity only upon FANCG inactivation, while FANCC deficient cells remained unaffected (our own unpublished results)." (PMID 26843614, 2016). "FANCC variant carriers were not identified in any of these FC cancer study groups." (PMID 36969007, 2023). "Inosine was the most expressed metabolite in FANCC-high cells, these metabolites could trigger the environment that induces inflammatory responses, activates metabolite pathways and leads to metabolic disorders, inflammation and ultimately cancer." (PMID 29930218, 2018). "Among the interface genes in the Her2+_TNBC module, the known cancer-related genes are mostly DNA repair genes, such as BARD1, BRIP1, BRCA1, BRCA2, FANCA, FANCC, FANCD2, and FEN1." (PMID 35992864, 2022). "The cancer-related genes BCL6, FANCC, PICALM and SGK1 were included among the target genes of the 64 TFBSs." (PMID 34316701, 2021). "FANCE methylation levels in different cancers showed the opposite trend, upregulated in KIRP and downregulated in LUSC, while FANCC methylation was upregulated in THCA and downregulated in UCEC." (PMID 34869316, 2021). "HPV integration is most frequently detected in genic regions, most often cancer-related genes, such as oncogenes (e.g., TP63, MYC, ERBB2) or tumor suppressor genes (e.g., BCL2, FANCC, HDAC2, RAD51B, CSMD1) and to a lesser extent in miRNA regions." (PMID 34439243, 2021). "Two studies using whole-exome-sequencing and DNA sequencing targeting 287 cancer-related genes respectively, found that alterations in DNA repair genes may correlate with response to chemotherapy: ERCC2, ATM, RB1, and FANCC." (PMID 36322407, 2022). "The FANCC knockout rearrangement pattern comprised mainly short tandem duplications and short deletions (<10 Kb) and also had other rearrangement classes but essentially echoed those of BRCA1-null cancers." (PMID 29717121, 2018). "While J21 cells are a sub-clone of a cancer cell line (HT1080) with known defects in DNA repair genes (e.g. ERCC5, FANCC, MSH3, and WRN), hTERTs are an immortalized, non-cancerous cell line that does not contain any known defects." (PMID 25893404, 2015).
tumor (32 papers, 2008 to 2026). "Tumor-associated genes on Chr9q such as FANCC, NTRK2, SYK, and NOTCH1 were amplified; amplification of BRAF, EZH2, MET, CDK6 and HGF located on Chr7 were also detected." (PMID 34895266, 2021). "There is insufficient data to indicate whether ATM and FANCC alterations are enriched in any taxonomical types, suggesting that combined tumor subtyping and mutational analysis could improve the ability to predict NAC response." (PMID 32635360, 2020). "Whether loss of FANCC played a role in the development of this tumor is unclear." (PMID 31362756, 2019). "Samples with biallelic loss of FANCC or FANCI were scored as fHRP, whereas one tumor with biallelic loss of FANCM (and intact BRCA1/2) was fHRD." (PMID 36805632, 2023). "Descriptive genomic analysis of pre-NAC tumor samples identified mutations in ERBB2 and DNA repair genes; ATM, RB1, FANCC, and ERCC2 were associated with tumor response to NAC." (PMID 33799514, 2021). "Using IPA analysis we found that cells with extopically expressed FANCC carried either elevated metabolites that are outcomes of tumor inhibitory forces, or the decreased metabolties that are driven by oncogenic potentials." (PMID 29930218, 2018). "In the tumor with integration in the FANCC gene, the expression of the gene fell between 1.5 and 3 times the IQR and was considered a mild outlier." (PMID 24586376, 2014). "In respect to non-tumor control, relative fold reduction in expression of these genes in primary tumors was seen in the following order: FANCC (31.6 ± 36.7) > PHF2 (26.54 ± 44.41) > PTCH1 (19.3 ± 27.8)." (PMID 18990233, 2008). "PTCH1 (350 Kb downstream to FANCC) is a key regulator in stem cell renewal hedgehog signaling pathway and functions as a tumor suppressor by inhibiting G1-S and G2-M phases of cell cycle." (PMID 18990233, 2008). "WGS also revealed a potentially disruptive FANCC translocation event in this tumor." (PMID 36964191, 2023). "Furthermore, deficiencies in CHEK2, FANCC, or NBN have been shown to induce PARPi sensitivity in other tumor models." (PMID 33339368, 2020). "We also found that FANCC can act in an FA-pathway-independent manner in tumor suppression." (PMID 29930218, 2018). "Analyses of 18 surgical HCC specimens yielded no further examples for genetic or epigenetic inactivation of FANCC, FANCF, or FANCG in HCC, suggesting a low prevalence of proximal FA pathway inactivation in this tumor type." (PMID 20509860, 2010). "Somatic alterations in pre-specified genes (ATM, RB1, FANCC and ERCC2) or increased tumor mutational burden did not improve the positive predictive value of cCR." (PMID 37783966, 2023). "Candidate pathogenic mutations in untranslated regions (UTRs) and BC-relevant genes regions, including oncogenes (i.e., KRAS, ERBB3, PIK3C2G) and tumor suppressor genes (i.e., FANCC, ATR, SMAD2), were found in organoids, and the majority of them were conserved within the tumor–organoid pair." (PMID 33371412, 2020). "However, some of these and other potential alternative driver genes identified in wildtype tumours such as KMT2A, FANCC and ERC1 were also identified in many of the RAS/RAF mutant cases." (PMID 26506417, 2015). "However, when considering only prospectively collected data and multivariable tests, FANCC (LRR, HR = 6.6, CI [2.99–19.05], p = 0.0002), circulating tumor cells (CTC) (DFS, HR 4.3, CI [1.7–10.9], p = 0.002) and PTCH1 (LRR, HR = 5.98, CI [2.37–15.07], p = 0.0001) showed the strongest associations." (PMID 36552043, 2022).
metabolic disorders (1 paper, 2018). "Here, we report roles of FA complementation C group protein (FANCC) in the protection from metabolic disorders." (PMID 29930218, 2018).
FANCC also shares sentences with these, for which no sentence is quoted: Fanconi anemia complementation group C (3 papers); hypogonadism (2); lung squamous cell carcinoma (2); mesothelioma (2); adenocarcinoma (1); alveolar rhabdomyosarcoma (1); alveolar soft part sarcoma (1); anaplastic astrocytoma (1); basal cell carcinoma (1); benign tumors (1); bladder cancer (1); breast and (1); cervical carcinoma (1); chromosomal disorder (1); craniosynostosis (1); deafness (1); endometrial cancer (1); Feingold syndrome (1); gastrointestinal disease (1); gastrointestinal stromal tumor (1); genetic diseases (1); giant cell tumor of bone (1); glioblastoma (1); hematological diseases (1); Hepatitis (1); Hepatitis B (1); Hodgkins lymphoma (1); juvenile polyposis syndrome (1); kidney cancer (1); leukemia (1).
A further 21 diseases each share a sentence with FANCC in 1 paper.